NRCAM (neuronal cell adhesion molecule)
Diseases named in the same sentence as NRCAM in open-access papers (continued):
Sharing a sentence is not in itself a finding about the gene and the disease.
psoriasis (1 paper, 2022). An autoimmune condition characterized by red, well-delineated plaques with silvery scales that are usually on the extensor surfaces and scalp. "Median serum NrCAM level was significantly decreased in patients with psoriasis compared to the controls (p < 0.05)." (PMID 36078974, 2022). "Serum concentrations of tau protein (MAPT), neuronal cell adhesion molecule (NrCAM) and neprilysin (NEP), which are NDs biomarkers and have been hardly studied in psoriasis before, were measured before and after 12 weeks of treatment with acitretin or methotrexate." (PMID 36078974, 2022). "Although there was no direct correlation between NrCAM and BMI, the highest concentrations were noted in obese patients which might point to links with adipose tissue or perhaps chronic metaflammation increasing within the weight observed in psoriasis." (PMID 36078974, 2022).
pulmonary fibrosis (1 paper, 2019). Chronic progressive interstitial lung disorder characterized by the replacement of the lung tissue by connective tissue, leading to progressive dyspnea, respiratory failure, or right heart failure. "NrCAM is a member of the immunoglobulin superfamily and is important in cell adhesion and thought to be involved in immunity and pulmonary fibrosis." (PMID 30990820, 2019).
retinoblastoma (1 paper, 2022). A malignant tumor that originates in the nuclear layer of the retina. "The study presented focuses on the role of the neuronal cell adhesion molecule L1 cell adhesion molecule (L1CAM) in retinoblastoma (RB), the most common malignant intraocular childhood tumor." (PMID 34228897, 2022).
substance abuse (1 paper, 2022). The use of a drug for a reason other than which it was intended or in a manner or in quantities other than directed. "Previous observations indicate that the NRCAM gene also affects drug-induced reward, and that genetic variability of the gene may be associated with expression levels as well as substance abuse vulnerability." (PMID 36060062, 2022).
vitreous hemorrhage (1 paper, 2017). Blood extravasation in the vitreous humor. "The degree of vitreous hemorrhage was negatively correlated with NrCAM, NCAM-1 and DcR3 (R2 = 0.709, 0.669 and 0.563, respectively)." (PMID 29095861, 2017).
tumor (26 papers, 2007 to 2025). "Tumor tissue from five patients with HCC metastasis was profiled using scRNA-seq to explore the biological characteristics associated with elevated NRCAM expression." (PMID 37993901, 2023). "Our study explored the diagnostic and prognostic utility of NRCAM not only using TCGA tumor expression profiles but also in serum." (PMID 37993901, 2023). "Our observation that focal immunostaining was rare in the normal thyroid, while such staining was common in tumours, indicated that elevated NrCAM expression is specific for tumour cells and represents a true tumour-associated abnormality." (PMID 17667921, 2007). "The aim of this study was to examine the expression of this adhesion molecule by analysing both transcript and protein levels in a series of PTCs/paired normal tissues, and to investigate the association of NrCAM expression with tumour grade and stage." (PMID 17667921, 2007). "Whether this tumor cell line-associated short NRCAM isoform is expressed as a protein remains unknown." (PMID 36499391, 2022). "Because NrCAM overexpression was seen in all examined cases, we assessed whether it could be associated with tumour progression or metastasis." (PMID 17667921, 2007). "The in vivo tumor allografts demonstrated that NRCAM mediated intra-hepatic/lung HCC metastasis by enhancing the ability of LCSCs to escape from tumors into the bloodstream." (PMID 37993901, 2023). "RNA sequencing (RNAseq) of PDX tumor (first generation) confirmed that PDX2 tumor tissue had a higher NRCAM expression level compared to PDX1 tumor tissue." (PMID 37993901, 2023). "Tumor size and weight of bilateral uterine horns including tumors were evaluated after 16-day NrCAM and/or MPA treatment." (PMID 35388173, 2022). "EC xenografts in BALB/C nude mice demonstrated that MPA combined with NrCAM had an increased tumor inhibitory effect compared with MPA or NrCAM alone." (PMID 35388173, 2022). "The tumour to paired normal tissue ratio of NrCAM mRNA levels ranged from 1.3 to 30.7 (average 5.7)." (PMID 17667921, 2007). "Quantitative reverse transcriptase (QRT)-PCR revealed that NrCAM expression was upregulated in all PTCs compared to normal thyroid, whatever the stage or size of the primary tumour." (PMID 17667921, 2007). "Expression of the NrCAM transcript was significantly higher (P<0.0001) in tumours (mean normalised expression 0.12±0.05), than in normal thyroid (0.021±0.019)." (PMID 17667921, 2007). "In summary, we found induction and overexpression of NrCAM in tumours arising from cells that very rarely express this cell-adhesion molecule in normal tissue." (PMID 17667921, 2007). "Most of the PTCs analysed (43/46) were positive for NrCAM expression, which was confined to tumour cells." (PMID 17667921, 2007). "Immunohistochemistry (IHC) confirmed that the expression of NrCAM was considerably higher in tumours (score 2+/3+) than in adjacent normal paratumoural thyroid tissue." (PMID 17667921, 2007). "In the normal thyroid and tissues surrounding tumours, focal NrCAM immunolabelling was seen only in follicles containing tall cells, where staining was restricted to the apical pole of thyrocytes." (PMID 17667921, 2007). "It has recently been reported that NrCAM is also expressed in a variety of other tissues, endothelial cells, certain tumour cell lines, and human cancers." (PMID 17667921, 2007). "In cancer samples, the intensity of the NrCAM protein band varied between cases; however, the reactive protein level in tumours was substantially higher than in normal thyroid tissues." (PMID 17667921, 2007). "In all cases, the levels of immunoreactive NrCAM protein were higher in tumours than in normal paired tissues." (PMID 17667921, 2007). "Because primary tumours contain both cancer cells and a variety of stroma cells, it was important to carefully examine the localisation of the NrCAM protein." (PMID 17667921, 2007).
tumor (continued). "Despite the fact that we have no data concerning the frequency of BRAFV600E in the present series of tumours, NrCAM transcript expression was significantly higher in every analysed cancer." (PMID 17667921, 2007). "In conclusion, CHL1 and NrCAM as members of the L1 superfamily may play an important role in early tumor development." (PMID 31989042, 2019). "Moreover, the β-value of NRCAM was significantly lower in FAP IME neoplasms than sporadic IME CRC (P = 0.001)." (PMID 30220972, 2018). "Moreover, FGF13, SEMA4D, PAPD6B and NRCAM were found to be commonly up-regulated in both cells and tumours." (PMID 30208958, 2018). "Furthermore, target genes of the canonical Wnt pathway, WISP-1 (WNT1-inducible-signaling pathway protein 1) and NRCAM (neuronal cell adhesion molecule), were upregulated 13.7- and 148.7-fold, indicating activation of the Wnt pathway in DC-tumor fusion cells." (PMID 26605345, 2015). "Finally, many of the genes down-regulated by EZH2 GOF in this study that modulate ECM-adhesion/signaling display altered expression or have been ascribed roles in tumor biology (e.g. NRCAM, CEACAM1, SORCS1, ADAM23, MME)." (PMID 25671303, 2015). "It has recently been shown that artificially raised expression of RET/PTC1 – one of two most prevalent RET/PTC variants found in the vast majority of PTCs – in normal human thyrocytes, directly induces many inflammatory and tumour-invasion genes including the NrCAM gene." (PMID 17667921, 2007). "In some tumours, membranous, both apical and basal, NrCAM localisation was also observed." (PMID 17667921, 2007). "Furthermore, 85% (39/46) of PTC tumours displayed intense (2+/3+) NrCAM immunoreactivity in >70% of cells." (PMID 17667921, 2007). "The relative amount of NrCAM transcript was significantly higher whatever the tumour stage or size." (PMID 17667921, 2007). "Therefore, we speculate that NRCAM may promote BNST progression by influencing T cell-mediated tumor immune responses to cancer cells." (PMID 38331905, 2024). "Furthermore, MPA combined with NrCAM had a better tumor inhibitory effect than MPA or NrCAM alone." (PMID 35388173, 2022). "Thus, the expression of CHL1, NrCAM, L1CAM, and ALCAM may be associated with a less aggressive tumor and, as a consequence, with a better prognosis." (PMID 31989042, 2019). "Thus, the tumor may initially still be able to translate and transcribe NrCAM, but loses this ability within progression." (PMID 31989042, 2019). "Nevertheless, NCAM1, NRCAM, SLIT2, ALCAM, NRP1, and NRP2 also showed mild expression in Stage 4 tumor cells (primarily in cluster cIV)." (PMID 40448172, 2025). "The expression of polysialic acid (polySia) on the neuronal cell adhesion molecule (NCAM) is called NCAM-polysialylation, which is strongly related to the migration and invasion of tumor cells and aggressive clinical status." (PMID 38731861, 2024). "It has also been demonstrated that NRCAM, LRFN4, and PHGDH are upregulated in CRC tissues compared to normal samples around the tumor and serve as predictors of poor clinical outcomes in advanced CRC patients 42-44." (PMID 38706895, 2024). "However, neither tumour stage nor size was associated with the overexpression of NrCAM." (PMID 17667921, 2007). "A large number of oncogenes as target genes of miR-505 in tumor cells, including TGF-α, HMGB1, FZD4, IGF1R, WNT7B, MAP3K3, NRCAM, and RUNX2, have been recognized as direct target genes of miR-505." (PMID 33520999, 2020). "The level of overexpression of the NrCAM mRNA in tumourous tissue appeared to be independent of the primary tumour stage (pT) or the size of the PTC." (PMID 17667921, 2007). "Strong NrCAM immunolabelling was found irrespective of the tumour stage or size, including clinically quiescent micro-carcinomas." (PMID 17667921, 2007). "Several lines of evidence indicate that expression of NrCAM and other members of the L1-CAM family might be important in the biological behaviour of human tumours." (PMID 17667921, 2007).
tumor (continued). "The immunostaining pattern of papillary tumours, peritumoural, and normal thyroid tissues unequivocally demonstrated that NrCAM is expressed by tumour cells and not merely by nervous components of the thyroid gland." (PMID 17667921, 2007).
cancer (24 papers, 2007 to 2025). A tumor composed of atypical neoplastic, often pleomorphic cells that invade other tissues. "The NRCAM over-expression has been associated with cancer progression and metastasis, but which isoform of NRCAM is responsible for this observed effect remains understudied." (PMID 36499391, 2022). "Among the PTCs examined in the present study there were only four cases of the follicular variant of PTC, and in these carcinomas the NrCAM transcript was overexpressed in comparison with normal thyroid." (PMID 17667921, 2007). "Moreover, overexpression of NrCAM elevates cancer cell motility and invasiveness in vitro and has been linked to a poor prognosis in adult patients." (PMID 31989042, 2019). "Recent reports have linked NrCAM expression with metastatic processes in particular human cancers." (PMID 17667921, 2007). "However, our in vivo models only explored NRCAM expression in cancer cells; it may be interesting for future studies to explore the metastatic contribution of NRCAM in blood vessel-associated cells." (PMID 37993901, 2023). "For instance, the top pathways in males included signaling by receptor tyrosine kinases, the Rap1 signaling pathway, and pathways in cancer, while in females, the top pathways were the Hippo signaling pathway, dopaminergic neurogenesis, and NrCAM interactions." (PMID 40629459, 2025). "Next, the β-catenin protein translocates to the nucleus, where it interacts with T-cell factors (TCFs) to regulate gene expressions, such as MYC and NRCAM, to accelerate the cell cycle and promote cancer cell metastasis." (PMID 39252305, 2024). "NRCAM is highly expressed in various cancers, including pediatric neuroblastoma, melanoma, colon, pancreatic, and thyroid cancer." (PMID 37993901, 2023). "The genes assayed were neuroendocrine-associated genes (INSM1, ASCL1, NRCAM, and SNAP25), one gene centered in the gene regulatory network (NUF2), and five possibly cancer-associated genes (PTP4A3, RFC4, REST, APEH, and FBLN2)." (PMID 34395507, 2021). "An increased expression of NrCAM has been correlated to metastatic development and tumorigenesis in different human cancers." (PMID 31989042, 2019). "IPA analysis of these unique up-regulated genes indicated that some genes were associated with cell transformation during cancer progression (ABL1, TRIO, FOSB, NRCAM, TRIB2 and CDK6) and others with cell survival (e.g., BCL10, BBC3, FGF8, HSPA4 and SOD1)." (PMID 29137349, 2017). "We proposed a mechanism in which the up-regulation of DVL3 eventually activated the target gene NRCAM, which may promote cancer cell proliferation and metastasis." (PMID 39252305, 2024). "The gene coding for NCAM1, a neuronal cell adhesion molecule with key features for motility regulation in neurons as well as in cancer cells, was significantly increased in expression and its promoter region showed a significant reduction in CpG methylation after ephrinA5 stimulation." (PMID 37880732, 2023). "Polysialic acid (polySia) is a unique carbohydrate polymer expressed on the surface of NCAM (neuronal cell adhesion molecule) in a number of cancers where it modulates cell-cell and cell-matrix adhesion, migration, invasion and metastasis and is strongly associated with poor clinical prognosis." (PMID 27611649, 2016). "In addition, cell-cell adhesion, in which NRCAM is known to play a part, has been well documented as being involved in cancer formation." (PMID 21281495, 2011). "NRCAM promotes cellular growth and differentiation, SERPINF1 inhibits angiogenesis in the prostate, and complements are peptidases that aid in cancer development." (PMID 32764784, 2020).
psychiatric disorder (8 papers, 2019 to 2026). A disorder characterized by behavioral and/or psychological abnormalities, often accompanied by physical symptoms. "Previous studies have shown that NrCAM imbalance might be involved in the occurrence of MDD and NrCAM served as one of risk factors for mental illnesses." (PMID 33912082, 2021).
neurological diseases (4 papers, 2013 to 2021). "Anti-IgLON5 disease is a progressive neurological disorder associated with autoantibodies against a neuronal cell adhesion molecule, IgLON5." (PMID 33917676, 2021). "Weaver is a neurological disease and while NRCAM, PNPLA8, and CTTNBP2 are all expressed in nervous tissues, overall NRCAM is expressed at higher levels across all nervous tissues, including the spinal cord." (PMID 23527149, 2013).
brain diseases (2 papers, 2012 to 2022). "For example, L1 neuronal cell adhesion molecule (L1CAM) was considered a BDEV marker, and attempts were made to analyze brain diseases via L1CAM-positive EVs in the blood." (PMID 36611896, 2022).
infection (2 papers, 2025). The state of being infected such as from the introduction of a foreign agent such as serum, vaccine, antigenic substance or organism. "To validate our findings, we treated HuLEC with an anti-NRCAM antibody prior to infection." (PMID 40162795, 2025).
NRCAM also shares sentences with these, for which no sentence is quoted: liver cancer (3 papers); neurodevelopmental disorder (3); prostate carcinoma (3); dementia (2); adenoma (1); allergic disease (1); Ataxia (1); bipolar disorder (1); brain cancer (1); chronic inflammatory demyelinating polyneuropathy (1); CNS tumors (1); COVID-19 (1); delirium (1); developmental delay (1); embryonic tumors (1); endometrial cancer (1); ependymoma (1); Ewing sarcoma (1); follicular adenomas (1); gynecological disease (1); hepatocellular carcinoma (1); Immunodeficiency (1); Intellectual disability (1); ischemic stroke (1); mental disorder (1); metastatic tumors (1); methamphetamine dependence (1); myoclonic epilepsy (1); neurodegenerative disease (1); obsessive-compulsive disorder (1).
A further 18 diseases each share a sentence with NRCAM in 1 paper.